RNU6-699P (RNA, U6 small nuclear 699, pseudogene)
Gene: Small nuclear RNA gene on chromosome 4 (66,897,262 to 66,897,371, forward strand). Ensembl gene ENSG00000252890.
Homologues: Orthologues: chimpanzee U6 (99% identical), macaque U6 (94% identical), dog RNU6-699P (66% identical), guinea pig U6 (65% identical), guinea pig U6 (64% identical), guinea pig U6 (63% identical), guinea pig U6 (61% identical), guinea pig U6 (58% identical), pig U6 (54% identical), pig U6 (53% identical). Paralogues in human: RNU6-1145P (75% identical), RNU6-38P (75% identical), RNU6-1214P (74% identical), RNU6-20P (74% identical), RNU6-476P (74% identical), RNU6-1316P (73% identical), RNU6-435P (73% identical), RNU6-639P (73% identical), RNU6-74P (73% identical), RNU6-144P (72% identical), RNU6-616P (72% identical), RNU6-1031P (71% identical), and 1285 more.